HP (haptoglobin)
Description:
As a result of hemolysis, hemoglobin is found to accumulate in the kidney and is secreted in the urine. Haptoglobin captures, and combines with free plasma hemoglobin to allow hepatic recycling of heme iron and to prevent kidney damage. Haptoglobin also acts as an antioxidant, has antibacterial activity, and plays a role in modulating many aspects of the acute phase response. Hemoglobin/haptoglobin complexes are rapidly cleared by the macrophage CD163 scavenger receptor expressed on the surface of liver Kupfer cells through an endocytic lysosomal degradation pathway. The uncleaved form of allele alpha-2 (2-2), known as zonulin, plays a role in intestinal permeability, allowing intercellular tight junction disassembly, and controlling the equilibrium between tolerance and immunity to non-self antigens.
Synonyms: HP2ALPHA2; HPA1S
Tractability: Small molecule: a structure with a bound ligand is known. Antibody: its Gene Ontology location is reachable by antibodies, with high confidence; UniProt places it where antibodies can reach, with medium confidence; UniProt predicts a signal peptide or a membrane-spanning region. PROTAC: ubiquitination databases record sites on it; its protein half-life has been measured.
Gene: Protein-coding gene on chromosome 16 (72,054,505 to 72,061,071, forward strand). Ensembl gene ENSG00000257017.
Subcellular location: Secreted
Subcellular location (Human Protein Atlas): Vesicles; Predicted to be secreted
Pathways (Reactome):
Immune System: Neutrophil degranulation
Vesicle-mediated transport: Scavenging of heme from plasma
Gene Ontology:
Molecular function: hemoglobin binding; protein binding; serine-type endopeptidase activity
Biological process: inflammatory response; negative regulation of hydrogen peroxide catabolic process; response to hydrogen peroxide; defense response; zymogen activation
Cellular component: blood microparticle; extracellular exosome; extracellular region; haptoglobin-hemoglobin complex; endocytic vesicle lumen; specific granule lumen; tertiary granule lumen
Genetic constraint (gnomAD): Loss-of-function variants: 14 observed, 21.6 expected, observed/expected ratio (o/e) 0.65, 90% interval 0.43 to 1.01. The upper end of that interval is the gene's LOEUF score, 1.01, which puts it in group 4 of 6, group 1 being the genes least tolerant of losing a copy. Missense variants: 370 observed, 390.85 expected, observed/expected ratio (o/e) 0.95, 90% interval 0.87 to 1.03. Synonymous variants: 135 observed, 147.79 expected, observed/expected ratio (o/e) 0.91, 90% interval 0.79 to 1.05.
Homologues: Orthologues: rabbit HP (72% identical), dog DHODH (69% identical), mouse Hp (68% identical), rat Hp (68% identical), tropical clawed frog cfi (17% identical), Drosophila melanogaster CG31266 (14% identical), Drosophila melanogaster CG31267 (12% identical). Paralogues in human: HPR (78% identical), C1S (28% identical), C1R (28% identical), C1RL (22% identical), F7 (20% identical), F10 (19% identical), KLKB1 (19% identical), F9 (18% identical), HGFAC (18% identical), F11 (17% identical), F12 (17% identical), CFI (16% identical), and 4 more.
Diseases named in the same sentence as HP in open-access papers:
HP is named in the same sentence as 485 diseases in open-access papers, as found by Europe PMC text mining. Sharing a sentence is not in itself a finding about the gene and the disease. The quoted sentences say what the papers report.
anemia (123 papers, 2010 to 2026). A reduction in the number of red blood cells, the amount of hemoglobin, and/or the volume of packed red blood cells. "These indicators stand for the possible inflammation, anemia, liver disease, hyperlipidemia, hyperglycemia, which were reported to have an association with the changes in serum HP concentrations." (PMID 36631470, 2023). "Previous studies have indicated that serum HP elevation or phenotypes are involved in hepcidin-induced iron deficiency anemia and disease outcomes in KD." (PMID 33344384, 2020). "The most severe forms of anemia were associated with lower haptoglobin concentrations suggesting ongoing erythrocyte destruction and release of free hemoglobin." (PMID 30150696, 2018). "Clinical risk factors for severe RBV-induced anemia include impaired renal function, age, dose per body weight, female gender, baseline platelet levels, baseline hemoglobin levels, and haptoglobin phenotype." (PMID 26438033, 2015). "However, abnormal values of LDH, haptoglobin, bilirubin, and creatinine depict a hemolytic cause of anemia and thrombocytopenia." (PMID 34367781, 2021). "The measurement of the mean corpuscular volume, reticulocyte count, and haptoglobin may better elucidate the interrelations between the risk factors for anemia." (PMID 28615254, 2017). "However, the haptoglobin levels should be interpreted with caution in the HD patients, since many conditions such as hemolysis, folate deficiency, liver disease, anemia, infection or inflammation can lead to haptoglobin variations." (PMID 22470525, 2012). "Reduced levels of haptoglobin may be reflective of enhanced hemolysis and may predispose anemia." (PMID 40725013, 2025). "Laboratory evaluation demonstrated anemia (hemoglobin 6.3-7.9 g/dL), microcytosis, elevated lactate dehydrogenase, indirect hyperbilirubinemia, low serum haptoglobin, moderate splenomegaly and reticulocytosis, consistent with ongoing hemolysis." (PMID 42291950, 2026). "During hospitalization, worsening anemia with positive direct antiglobulin testing, peripheral spherocytes, reticulocytosis, hyperbilirubinemia, low haptoglobin, and splenomegaly supported the diagnosis of warm autoimmune hemolytic anemia." (PMID 42093808, 2026). "Imaging showed posterior reversible encephalopathy syndrome (PRES), and labs revealed anemia, thrombocytopenia, low haptoglobin, elevated LDH, and schistocytes." (PMID 41664793, 2026). "Laboratory findings revealed severe anemia with hemoglobin of 4.4 g/dL, elevated lactate dehydrogenase, low serum haptoglobin, and positive direct antiglobulin test (DAT) for IgG, consistent with warm AIHA." (PMID 40497195, 2025). "Laboratory tests revealed mild anemia (hemoglobin: 11.8 g/dL), elevated total bilirubin (1.27 mg/dL), and undetectable haptoglobin (<10 mg/dL), suggesting ongoing hemolysis." (PMID 41040783, 2025). "Laboratory evaluation revealed severe thrombocytopenia and anemia, along with elevated lactate dehydrogenase, undetectable haptoglobin, and increased total bilirubin." (PMID 40827194, 2025). "In this case, the patient developed classic features of aHUS in the postpartum period, including schistocytosis, elevated LDH, low haptoglobin, anemia, thrombocytopenia, and worsening renal function requiring dialysis." (PMID 40951196, 2025). "The laboratory evaluation revealed severe renal dysfunction (sCr 4.08 mg/dL), markedly elevated LDH (1142 U/L), undetectable haptoglobin, moderate normocytic anemia, and significant thrombocytopenia." (PMID 40422585, 2025). "He required transfusions of red blood cells and haptoglobin, after which anemia and jaundice improved." (PMID 39877320, 2025). "Severe anemia with hemolytic features requires prompt and comprehensive evaluation, including reticulocyte count and serum haptoglobin." (PMID 40842790, 2025).
anemia (continued). "Initial examination revealed severe anemia with elevated levels of bilirubin, reticulocytes, lactate dehydrogenase, decreased levels of haptoglobin, and a positive direct antihuman globulin test." (PMID 40228248, 2025). "Laboratory findings showed normocytic anemia, elevated reticulocytes, high lactate dehydrogenase, indirect hyperbilirubinemia, and undetectable haptoglobin levels." (PMID 39677145, 2024). "In cases of anemia associated with reticulocytosis, elevated lactate dehydrogenase (LDH), low haptoglobin, and elevated indirect bilirubin, AIHA should be suspected." (PMID 39156320, 2024). "The diagnostic workup in our case indicated low hemoglobin, increased LDH, and low haptoglobin levels, indicating hemolysis, along with a history of recurrent anemia and thrombocytopenia." (PMID 39156320, 2024). "Biologically, classic markers of haemolysis are always present: regenerative anaemia, unconjugated hyperbilirubinemia, low haptoglobin, and increased lactate dehydrogenase (LDH)." (PMID 39144870, 2024). "Ineffective erythropoiesis should be suspected if there is inadequate reticulocytosis to the degree of anemia despite erythroid hyperplasia; indirect hyperbilirubinemia and low haptoglobin indicate ongoing intramedullary and extramedullary hemolysis." (PMID 36817311, 2023). "Seven days after admission, we observed a worsening of anemia and thrombocytopenia with haptoglobin reduction, lactic dehydrogenase increase and presence of schistocytes on morphological examination of peripheral blood." (PMID 38115241, 2023). "Monitoring of blood parameters in patients with persistent anemia should include determination of serum haptoglobin." (PMID 36636594, 2023). "The patient developed hypertension in the 2nd week, followed by high lactate dehydrogenase (1010 U/L), schistocytes (5 per hpf), low haptoglobin (< 5 mg/dl), thrombocytopenia, and anemia in the 3rd week." (PMID 36915123, 2023). "When there is anemia due to intravascular hemolysis of RBCs, haptoglobin levels are expected to fall." (PMID 37091678, 2023). "Of note, repeated laboratory investigations showed normal serum haptoglobin concentrations in our patient despite active iTTP with anemia and thrombocytopenia." (PMID 36576539, 2023). "Labs revealed hemolysis with elevated lactate dehydrogenase, low haptoglobin, anemia, and thrombocytopenia, but otherwise unremarkable immunology labs." (PMID 35428247, 2022). "Labs revealed anemia, thrombocytopenia, elevated lactate dehydrogenase, and low haptoglobin with normal serum creatinine." (PMID 35812544, 2022). "Blood work demonstrated anemia, severe thrombocytopenia, elevated lactate dehydrogenase, decreased haptoglobin, and elevated creatinine, and peripheral blood smear showed marked schistocytosis indicating MAHA." (PMID 35989829, 2022). "TMA features (thrombocytopenia (92.2%), anemia (96.5%), low haptoglobin levels (90.4%) and schistocytes (79.3%)) were present in most patients." (PMID 35057750, 2022). "In many cases of CIA however, substantial hemolysis, evident from haptoglobin consumption, contributes to anemia as do other contributing factors such as EPO and vitamin deficiencies." (PMID 33842333, 2021). "In pre-clinical studies, anemia due to extravascular hemolysis in the spleen was observed, as indicated by decreased plasma haptoglobin, and serum levels of bilirubin together with a hypercellular marrow and reticulocytosis." (PMID 33216844, 2020). "A mass spectrometry-based quantitative proteomic analysis indicated anemia of these rats, which presented with significant downregulation of hemoglobin and haptoglobin." (PMID 32238420, 2020). "The patient died at 6 years old suffering from growth retardation, anaemia, leukocytosis, thrombocytosis, coagulation abnormality, elevated serum levels of haptoglobin, ferritin and haem, a low serum bilirubin concentration and hyperlipidaemia." (PMID 32611348, 2020).
anemia (continued). "One key parameter distinguishing our models of SMA and moderate anaemia was rapid haemolysis, as assessed by an accelerated drop in plasma haptoglobin levels in infected rhesus compared to infected cynomolgus macaques." (PMID 31831787, 2019). "His labs showed hyperbilirubinemia, anemia, elevated lactate dehydrogenase, and low haptoglobin, consistent with hemolytic anemia." (PMID 31772791, 2019). "He developed an acute kidney injury with anaemia, thrombocytopaenia, raised lactate dehydrogenase, low haptoglobin, and red cell fragments." (PMID 29862099, 2018). "Discontinuing valproic acid reversed the anemia, thrombocytopenia, and normalized the LDH and haptoglobin, supporting a drug-induced cause for the TMA." (PMID 28774273, 2017). "Initial investigations revealed severe anemia with appropriate reticulocytosis, severely elevated lactate dehydrogenase, undetectable haptoglobin level and positive direct coombs test." (PMID 28239468, 2017). "Haptoglobin levels are measured in systematic lupus erythematosus patients as part of the workup for anemia, with low levels indicating hemolysis." (PMID 28203576, 2017). "This can present as anemia on admission with evidence of hemolysis as indicated by low serum haptoglobin, high serum lactate dehydrogenase (LDH), elevated indirect bilirubin, and spherocytosis." (PMID 26090240, 2015). "This can present as anemia on admission with evidence of hemolysis as indicated by low haptoglobin, high LDH, elevated indirect bilirubin, and spherocytosis." (PMID 26090240, 2015). "Normal haptoglobin and elevated reticulocyte percentage support bleeding rather than hemolysis as the cause of anemia." (PMID 40568284, 2025). "Diagnostic test results typically align with signs of intravascular red blood cell breakdown, including anemia, increased reticulocyte levels, diminished haptoglobin, elevated lactate dehydrogenase, hemoglobin in urine and a negative Coombs test (except in pneumococcal HUS)." (PMID 40217974, 2025). "Relying on schistocyte presence as the single diagnostic criterion would lead to missed diagnosis in 23.8% (STEC-HUS) to 86.4% (BMT) of patients (for anemia: 8.2%–22.3%; thrombocytopenia: 31.8%–67.9%; high LDH: 10.0%–40.7%, low haptoglobin: 0%–70.4%, according to the causes of TMA)." (PMID 40630316, 2025). "In the absence of anemia, normal plasma haptoglobin, and a normal Coombs test, other causes of transient elevation in serum LDH were less likely in the patient described in this report." (PMID 39597031, 2024). "Persistent and progressive anemia, abnormally low reticulocyte count and elevated haptoglobin." (PMID 38957352, 2024). "Regarding monitoring of hematological parameters in stable GD patients on long‐term treatment who develop persistent anemia, panelists agreed that it should include determination of reticulocyte count, serum levels of vitamin B12, folic acid, iron and ferritin, and haptoglobin." (PMID 36636594, 2023). "We have established an outpatient clinic specializing in anemia to comprehensively assess the clinical laboratory data on anemia, including serum levels of haptoglobin, creatine kinase, folate, and vitamin B12 in addition to hemoglobin (Hb) and ferritin as a fundamental assessment for the athletes." (PMID 35237470, 2022). "Evaluation for other causes of anemia should be performed with additional laboratory testing including iron and ferritin levels, B12 and folate levels, hemolysis work‐up with lactate dehydrogenase (LDH), and haptoglobin." (PMID 35280084, 2022). "Anaemia due to vitamin B12 deficiency is often associated with intramedullary haemolysis responsible for high level of LDH and low haptoglobin and sometimes the presence of numerous schistocytes on the blood smear, and can also be associated with thrombocytopenia." (PMID 33260979, 2020).
anemia (continued). "Across all dose levels, anaemia occurred in approximately 80% of patients (14% grade 3) and generally had characteristics consistent with a haemolysis mechanism (increase in reticulocyte count, decrease in haptoglobin level)." (PMID 30318513, 2018). "Diagnosis of AIHA is relatively easy given the constellation of laboratory findings of normocytic or macrocytic anemia, reticulocytosis, low serum haptoglobin levels, elevated LDH level, increased indirect bilirubin level and a positive direct antiglobulin test." (PMID 28239468, 2017). "Laboratory findings indicated mild anemia (hemoglobin: 11.8 g/dL; reference range, 11.9-14.9 g/dL), mildly elevated total bilirubin levels (1.27 mg/dL; reference range, 0.25-1.10 mg/dL), and undetectable haptoglobin (<10 mg/dL), suggestive of ongoing hemolysis." (PMID 41040783, 2025). "The lack of correlation between anti-PS antibody and haptoglobin levels may be due to the ability of anti-PS antibodies to cause anemia through phagocytosis by macrophages as shown in mice and not only by hemolysis." (PMID 37091678, 2023). "In mice with ECM, anemia was only mild to moderate whereas inflammation is overwhelming, and this might help to explain why haptoglobin levels were high, since haptoglobin is an acute phase protein that increases with conditions such as inflammation and infection." (PMID 34103601, 2021). "Therefore, our results suggest that the effects of reproductive anemia, perhaps mediated by haptoglobin, might extend to several other physiological systems in post-laying females." (PMID 30479645, 2018). "Laboratory tests revealed moderate anemia, elevated LDH, low haptoglobin, and significant proteinuria (4.84 g/24h)." (PMID 42011441, 2026). "TMA syndromes, which include TTP, often present with MAHA, schistocytes on peripheral blood smear in the setting of anemia, thrombocytopenia, abnormal LDH, haptoglobin, and indirect hyperbilirubinemia." (PMID 41466911, 2025). "Laboratory profile of the patient demonstrating anemia, thrombocytopenia, indirect hyperbilirubinemia, elevated LDH, and markedly reduced haptoglobin, consistent with intravascular hemolysis." (PMID 41450399, 2025). "Labs showed anemia, thrombocytopenia, macrocytosis, elevated lactate dehydrogenase (LDH), low haptoglobin, elevated D-dimer, and a positive intrinsic factor blocking antibody leading to a diagnosis of pernicious anemia." (PMID 40357099, 2025). "Initial laboratory tests revealed severe anemia (Hb 5.6 g/dL), elevated LDH, indirect hyperbilirubinemia, undetectable haptoglobin, and a positive direct antiglobulin test (DAT) for IgG, confirming warm AIHA." (PMID 41220968, 2025). "Lab tests showed low platelets, anemia, high LDH, undetectable haptoglobin, high bilirubin, and very low ADAMTS13 activity with high inhibitor levels, confirming acquired TTP." (PMID 40827194, 2025). "Hemolytic anemia tests include blood count, platelet count, peripheral blood smear (for schistocytes), LDH, and haptoglobin." (PMID 39918340, 2025). "Biological parameters’ presence at the time of TMA diagnosis ranked as follows: anemia (81.7%), high LDH (75.4%), low haptoglobin (53.7%), thrombocytopenia (40.3%), and schistocytes > 1% (20.5%)." (PMID 40630316, 2025). "The presence of TMA-related parameters concerned virtually all patients with TTP but varied widely for the other patients as follows: anemia: 81.7%, high lactate dehydrogenase (LDH) (75.4%), low haptoglobin (53.7%), and thrombocytopenia (40.3%)." (PMID 40630316, 2025). "Other parameters such as anemia, elevated LDH, reduced haptoglobin, presence of schistocytes, and organ damage align with recommendations for other TMA forms." (PMID 39918340, 2025). "In the first case, the patient received the diagnosis of TA-TMA due to the presence of anemia, thrombocytopenia, elevated LDH, low haptoglobin, and proteinuria." (PMID 38773280, 2024).